PIK3C3 (phosphatidylinositol 3-kinase catalytic subunit type 3)
Description:
Catalytic subunit of the PI3K complex that mediates formation of phosphatidylinositol 3-phosphate; different complex forms are believed to play a role in multiple membrane trafficking pathways: PI3KC3-C1 is involved in initiation of autophagosomes and PI3KC3-C2 in maturation of autophagosomes and endocytosis. As part of PI3KC3-C1, promotes endoplasmic reticulum membrane curvature formation prior to vesicle budding. Involved in regulation of degradative endocytic trafficking and required for the abscission step in cytokinesis, probably in the context of PI3KC3-C2. Involved in the transport of lysosomal enzyme precursors to lysosomes (By similarity). Required for transport from early to late endosomes (By similarity). (Microbial infection) Kinase activity is required for SARS coronavirus-2/SARS-CoV-2 replication.
Synonyms: VPS34; hVps34
Tractability: Small molecule: a structure with a bound ligand is known; a high-quality ligand is known; it has a binding pocket of medium quality; it belongs to a druggable protein family. Antibody: its Gene Ontology location is reachable by antibodies, with high confidence. PROTAC: UniProt records ubiquitination sites on it; ubiquitination databases record sites on it; its protein half-life has been measured; a small molecule that binds it is known.
Target class: Enzyme; Transferase
Chemical probes: SAR405 (high quality), VPS34-IN-1 (high quality)
Gene: Protein-coding gene on chromosome 18 (41,955,207 to 42,087,830, forward strand). Ensembl gene ENSG00000078142.
Subcellular location: Midbody; Late endosome; Cytoplasmic vesicle, autophagosome
Pathways (Reactome):
Disease: Dengue virus modulates apoptosis; SARS-CoV-2 activates/modulates innate and adaptive immune responses; Translation of Replicase and Assembly of the Replication Transcription Complex
Metabolism: Synthesis of PIPs at the Golgi membrane; Synthesis of PIPs at the early endosome membrane; Synthesis of PIPs at the late endosome membrane
Immune System: Antigen Presentation: Folding, assembly and peptide loading of class I MHC; Toll Like Receptor 9 (TLR9) Cascade
Signal Transduction: PI3K Cascade; RHO GTPases Activate NADPH Oxidases
Autophagy: Macroautophagy
Gene Ontology:
Molecular function: 1-phosphatidylinositol-3-kinase activity; phosphatidylinositol kinase activity; protein binding; kinase activity; phosphotransferase activity, alcohol group as acceptor; protein kinase activity
Biological process: autophagosome assembly; autophagosome maturation; autophagy; early endosome to late endosome transport; host-mediated activation of viral genome replication; phosphatidylinositol phosphate biosynthetic process; phosphatidylinositol-3-phosphate biosynthetic process; positive regulation of natural killer cell mediated cytotoxicity; positive regulation of protein lipidation; regulation of autophagy; regulation of cytokinesis; regulation of macroautophagy; cellular response to glucose starvation; macroautophagy; pexophagy; phosphatidylinositol-mediated signaling; protein targeting to lysosome; endosome organization; phosphatidylinositol 3-kinase/protein kinase B signal transduction; protein processing; response to L-leucine; synaptic vesicle endocytosis
Cellular component: autolysosome; late endosome; membrane; midbody; phosphatidylinositol 3-kinase complex, class III; plasma membrane; axoneme; cytosol; endosome; peroxisome; phagocytic vesicle membrane; phagophore assembly site; phosphatidylinositol 3-kinase complex, class III, type I; phosphatidylinositol 3-kinase complex, class III, type II; autophagosome; GABA-ergic synapse; glutamatergic synapse; phagocytic vesicle; postsynapse; postsynaptic endosome; presynaptic endosome
Genetic constraint (gnomAD): Loss-of-function variants: 39 observed, 50.79 expected, observed/expected ratio (o/e) 0.77, 90% interval 0.59 to 1. The upper end of that interval is the gene's LOEUF score, 1, which puts it in group 4 of 6, group 1 being the genes least tolerant of losing a copy. Missense variants: 425 observed, 539.61 expected, observed/expected ratio (o/e) 0.79, 90% interval 0.73 to 0.85. Synonymous variants: 187 observed, 190.53 expected, observed/expected ratio (o/e) 0.98, 90% interval 0.87 to 1.11.
Homologues: Orthologues: chimpanzee PIK3C3 (99% identical), macaque PIK3C3 (99% identical), dog PIK3C3 (99% identical), guinea pig PIK3C3 (98% identical), rat Pik3c3 (98% identical), mouse Pik3c3 (98% identical), pig PIK3C3 (96% identical), rabbit PIK3C3 (93% identical), tropical clawed frog pik3c3 (93% identical), zebrafish pik3c3 (87% identical), Drosophila melanogaster Pi3K59F (59% identical), Caenorhabditis elegans vps-34 (39% identical). Paralogues in human: PIK3CB (25% identical), PIK3CD (25% identical), PIK3CA (23% identical), PIK3CG (23% identical), PIK3C2A (22% identical), PIK3C2B (22% identical), PIK3C2G (19% identical), PI4KA (15% identical), PI4KB (10% identical).
Diseases named in the same sentence as PIK3C3 in open-access papers:
PIK3C3 is named in the same sentence as 130 diseases in open-access papers, as found by Europe PMC text mining. Sharing a sentence is not in itself a finding about the gene and the disease. The quoted sentences say what the papers report.
breast carcinoma (25 papers, 2014 to 2025). "For instance, targeting PIK3C3-mTORC1 signaling, which regulates autophagy, in dormancy-prone breast cancer cells can blunt metastasis initiation." (PMID 40732251, 2025). "PRKCQ-AS1 also promotes breast cancer cell apoptosis and impairs paclitaxel resistance through miR-361-5p/PIK3C3-mediated autophagy." (PMID 40597380, 2025). "MDM2 ligase coupled with inhibitors of the targets BCL2, BRD4, CDK9, PLK1 and MCL1 in stomach tumor, and MDM2 with PIK3C3 inhibitors in breast cancer, seems to be the best therapeutic strategy." (PMID 35249548, 2022). "In a similar manner, the combination of MDM2 together with some PIK3C3 inhibitors in breast cancer was an attractive option." (PMID 35249548, 2022). "MDM2 ligase, coupled with inhibitors of the targets BCL2L1, BRD4, CDK9, PLK1 and MCL1 in stomach cancer, and MDM2 with PIK3C3 inhibitors in breast cancer seemed to be the best therapeutic construction." (PMID 35249548, 2022). "In an MCF-7 breast cancer cell model, PIK3C3 was found to stimulate ERK pathway-related tumor progression through protein kinase C-δ (PKC-δ)-mediated activation of p62." (PMID 34681622, 2021). "PIK3C3 plays a key role in many human cancers, including hepatocellular carcinoma (HCC), lung cancer, colorectal cancer (CRC), and breast cancer, but the underlying mechanisms involved in tumorigenesis remain elusive." (PMID 34681622, 2021). "PIK3C3 protein levels were significantly elevated in highly tumorigenic breast cancer cell lines (MDA-MB-231, MDA-MB-468, SKBR-3) compared with those with relatively low tumorigenic potential (MCF-7 and T47D)." (PMID 34681622, 2021). "Ultimately, targeting dormancy-specific vulnerabilities directly, such as the dependence on PIK3C3-mTORC1 signaling in dormancy-prone breast cancer cells could lead to either cell death or re-sensitization to conventional immune attack." (PMID 40732251, 2025). "PIM3 and PIK3C3 in breast cancer, PIM3 and PTEN in breast, kidney, and ovarian cancer, and PIM3 and PTEN in prostate cancer Malignancies of the liver and thyroid, as well as cancers of the breast and ovary, have been linked to PIK3C3 and PTEN mutations in the past." (PMID 35154620, 2022). "Stable expression of PIK3C3 in MCF-7 breast cancer cells dramatically increased the intracellular accumulation of p62, the expression of epithelial–mesenchymal transition (EMT) markers (snail and vimentin), and the invasion of cells in vitro with activation of the MEK-ERK pathway." (PMID 34681622, 2021). "Furthermore, the genetic knockdown of either PIK3C3 or ATG12 attenuated autophagy and re-sensitized breast cancer cells to doxorubicin." (PMID 38310598, 2024).
melanoma (19 papers, 2016 to 2025). A malignant, usually aggressive tumor composed of atypical, neoplastic melanocytes. "In contrast, loss of Vps34 (encoded by Pik3c3) in dendritic cells as well as monocytes/macrophages promoted lung metastasis by B16F10 melanoma cells." (PMID 33381037, 2020). "Inhibition of the autophagy-related protein PIK3C3/VPS34 in melanoma recruits NK and CD8+T cells into the tumor bed, and as such improves the efficacy of anti-PD-1/PD-L1 immunotherapy." (PMID 36003368, 2022). "Deleting PIK3C3 (a key player in autophagy) in dendritic cells contributes to reduced CD8α+ dendritic cells and B16 melanoma-specific CTL activity." (PMID 36230955, 2022). "In CT26 colon cancer cells and B16-F10 melanoma cells, targeting PIK3C3 with siRNA or PIK3C3 inhibitors reduced autophagy and tumor growth and improved mouse survival by inducing the infiltration of natural killer, CD8+, and CD4+ T effector cells." (PMID 34681622, 2021). "In models of CT26 CRC cells and B16-F10 melanoma cells, targeting PIK3C3 with SAR405 inhibited autophagy, significantly decreased tumor growth, and improved mouse survival by inducing the infiltration of natural killer, CD8+, and CD4+ T effector cells." (PMID 34681622, 2021). "In addition, inhibition of PIK3C3 reduced invasion and promoted the death of trametinib-resistant melanoma cells in an in vivo zebrafish xenograft of metastatic melanoma." (PMID 34681622, 2021). "Interestingly, the top two upregulated genes in melanomas from RHC were PRKAA1 (fold change=1.37, p=0.08) and PIK3C3 (fold change=1.23, p=0.09) while the top two downregulated were YWHAG (fold change=0.62, p=0.29) and CLN3 (fold change=0.77, p=0.3)." (PMID 28030792, 2017).
colorectal cancer (13 papers, 2015 to 2026). A primary or metastatic malignant neoplasm that affects the colon or rectum. "Another study in colorectal cancer (CRC) demonstrated that miR-338-5p induced EMT by suppressing PIK3C3 expression and autophagy, which indicates that autophagy inhibits EMT in CRC." (PMID 33937024, 2021). "In previous studies, to the best of our knowledge, the function of miR-338-5p in tumorigenesis was reported in only one study that regarded miR-338-5p as an oncomir inducing cell migration by suppressing PIK3C3 expression and autophagy in colorectal cancer." (PMID 27166996, 2016). "Regarding class III PI3K, miR-338–5p was thought to silence the expression of its catalytic subunit (PIK3C3, or Vps34) and suppress autophagy, thereby enhancing colorectal cancer cell migration." (PMID 25893379, 2015).
cardiac hypertrophy (8 papers, 2015 to 2025). "Studies have reported that PIK3C3-mediated prolonged activation of autophagy leads to cardiac hypertrophy in HSP-27 transgenic mice." (PMID 35629298, 2022). "PIK3C3-mediated prolonged activation of autophagy plays a critical role in the transition of cardiac hypertrophy in heat shock protein 27 transgenic mice." (PMID 35629298, 2022).
lung carcinoma (8 papers, 2017 to 2025). "Previously, SRSF1 has been indicated to inhibit autophagosome formation by reducing the accumulation of LC3-II and numbers of autophagosomes in lung cancer cells by directly binding to PIK3C3." (PMID 35333349, 2022). "Here, we reported that juglanin increased LC3, ATG7, Beclin1 and PIK3C3 expression, contributing to autophagy formation accompanied with the exterior of acidic vesicular organelles in lung cancer cells." (PMID 29212196, 2017). "SRSF1 inhibited autophagy by adjusting Bcl-x splicing and combining PIK3C3 in lung cancer." (PMID 38581057, 2024). "Inhibition of PIK3C3 using siRNA restrains nuclear EGFR localization and restores ARF expression, leading to the apoptosis of H1975 lung cancer cells." (PMID 34681622, 2021). "Beyond lung cancer, knockdown of GGH could result in the activation of the ULK1 complex and PI3KC3-C1 via the phosphorylation of ULK1 and PIK3C3 in a multitude of cancer cell lines." (PMID 40268350, 2025).
hepatocellular carcinoma (7 papers, 2017 to 2025). A malignant tumor that arises from hepatocytes. "Further, the autophagy level was decreased in hepatocellular carcinoma cells treated with a PIK3C3 inhibitor or small interfering RNAs (siRNA), which confirms PIK3C3 as an essential factor involved in the autophagy process." (PMID 35629298, 2022). "However poor survival rates were observed in patients with high expression of PIK3C3 in hepatocellular carcinoma." (PMID 35629298, 2022).
ovarian carcinoma (6 papers, 2014 to 2024). A malignant neoplasm originating from the surface ovarian epithelium. "Among them, there were genes important for signaling (Pik3c3), genes playing a role in breast (Nav3) and ovarian cancers (Epcam)." (PMID 31084621, 2019).
viral infection (6 papers, 2023 to 2025). "Notably, the most significant decreases in viral infection were observed with the loss of PIK3C3 and SLC39A9, resulting in a 70% and 50% reduction in viral infection respectively." (PMID 39173055, 2024). "Moreover, genetic depletion of PIK3C3 or SLC39A9 not only decreased virus infection but also significantly diminished EBOV RNA levels in infected cells and progeny virus production." (PMID 39173055, 2024). "Secondly, the functional roles attributed to PIK3C3 and SLC39A9 in EBOV infection are primarily based on viral infection assays conducted in vitro using genetic knockout cells, where the efficiency of knockout varied." (PMID 39173055, 2024). "In addition, knockdown and knockout of PIK3C3 resulted in the attenuation of PM-induced autophagy, thereby rescuing APN expression and viral infection." (PMID 39641621, 2025). "Importantly, the genetic complementation of PIK3C3 and SLC39A9 KO cells with their respective cDNAs restored EBOVΔVP30-EGFP viral infection to a level comparable to that of sgNC-transduced cells, excluding the off-target effect of the sgRNA." (PMID 39173055, 2024).
autoimmune disease (5 papers, 2022 to 2025). A disorder resulting from loss of function or tissue destruction of an organ or multiple organs, arising from humoral or cellular immune responses of the individual to their own tissue constituents. "PIK3C3 has been suggested to play an important role in autoimmune diseases." (PMID 35629298, 2022). "However, because of the limitation of samples, properly assessing the immune cells in terms of investigating the relationship between PIK3C3 and autoimmune disease in PIK3C3 overexpressed pigs still needs further study." (PMID 35629298, 2022). "While PIK3C3 is a member of the PI3K family, PIK3C3 plays a key role in T cell metabolism and CD4 + T cell-mediated autoimmune diseases and can also regulate autophagy through the AKT-mTOR pathway." (PMID 37817209, 2023).
colon cancer (5 papers, 2021 to 2025). "A recent report using yet another PIK3C3/VPS34 inhibitor showed similar anti-cancer effects in treating colon cancer by modulating the immune checkpoint regulators." (PMID 33946505, 2021). "In RKO colon cancer cells, PIK3C3 inhibition using shRNA or PIK-III (a PIK3C3 inhibitor) enhanced lysosomal delivery and degradation of the transferrin receptor, leading to persistent cellular iron deprivation and impaired cell growth." (PMID 34681622, 2021). "Overall, the current study provided conclusive evidence that inhibiting PIK3C3/VPS34 can help promote the efficacy of conventional colon cancer therapy." (PMID 33946505, 2021). "Taken together, it appears that inhibiting PIK3C3/VPS34 may significantly boost the anti-colon cancer therapy though additional studies using murine models of CRC progression and therapy resistance are needed and are part of our ongoing investigations." (PMID 33946505, 2021). "In the current study, we provided data supporting the efficacy of 36-077, a potent inhibitor of PIK3C3/VPS34, in inhibiting autophagy to kill the CSC to promote the efficacy of colon cancer therapy." (PMID 33946505, 2021).
liver cancer (5 papers, 2020 to 2025). An epithelial or non-epithelial malignant neoplasm that arises from the liver. "PIK3C3 controls the growth of liver cancer stem cells, and PIK3C3 inhibition inhibits the action of liver cancer stem cells brought on by PI3K inhibitor." (PMID 37790613, 2023). "SMAD2 and SMAD3 correlated with autophagy-related scores (based on ATG12, ATG7, ATG3, ATG5, ATG4B, PIK3C3, PRKAA2, and GABARAPL1) in liver cancer." (PMID 37790613, 2023).
pancreatic cancer (5 papers, 2016 to 2025). "A markedly high number of copy number deletions were also observed for the PIK3C3 gene in Pancreatic cancer (24%), whereas copy number amplifications for ATG9B (17%), ATG4B (16%) and MAP1LC3C (13%) were commonly found." (PMID 27256984, 2016). "Therefore, in pancreatic cancer, the effect of miR-338-5p on EMT by inhibiting PIK3C3 and autophagy is still unclear and needs further study." (PMID 33937024, 2021).
schizophrenia (5 papers, 2008 to 2022). A major psychotic disorder characterized by abnormalities in the perception or expression of reality. "Genetic analysis of the promoter region of PIK3C3 in patients with schizophrenia pointed to a mutation that probably results in diminished gene transcription." (PMID 26877878, 2016). "Accordingly, family-based association studies of schizophrenia have revealed PI3K class 3 (PIK3C3) genetic contributions to the pathogenesis of the disorder." (PMID 26877878, 2016). "A rare variant in the promoter of PIK3C3 gene has been reported to be associated with bipolar disorder and schizophrenia in a candidate gene study." (PMID 18429927, 2008). "Variations in PIK3C3 have been associated with bipolar and schizophrenia in numerous studies." (PMID 34573423, 2021). "POU3F1 was also proved to affect calcium flux through binding to the promoter region of PIK3C3 (MIM 602609), a member of the phosphatidylinositide 3-kinase family, and mutations in PIK3C3 have been shown to be involved in a subset bipolar disorder and schizophrenia patients." (PMID 20808825, 2010).
bipolar disorder (4 papers, 2008 to 2022). A disorder of the brain that causes unusual shifts in mood, energy, activity levels and the ability to carry out day-to-day tasks. "The locus on chromosome 18 at about 23 Mb that was associated with OF fecal boli contains the gene Pik3c3 which is involved in phosphoinositide lipid metabolism, a potential target for the therapeutic effect of lithium in bipolar disorder." (PMID 36712851, 2022). "A link between PIK3C3 and bipolar disorder might be consistent with the observation that PIs are potential targets for the therapeutic effect of lithium in bipolar disorder." (PMID 18429927, 2008).
bladder cancer (4 papers, 2016 to 2023). "MPT0L145 is a highly potent inhibitor of PIK3C3 with a Kd value of 0.53 nM with minor activity to FGFR that interferes autophagy flux in FGFR-activating bladder cancer cells." (PMID 31514441, 2019). "We previously identified that MPT0L145 is a PIK3C3/FGFR inhibitor that not only increases autophagosome formation due to fibroblast growth factor receptor (FGFR) inhibition but also perturbs autophagic flux via PIK3C3 inhibition in bladder cancer cells harboring FGFR activation." (PMID 31514441, 2019). "MPT0L145 is a PIK3C3/FGFR3 inhibitor which simultaneously promotes autophagosome formation via FGFR3 inhibition and impairs autophagy flux via PIK3C3 inhibition in bladder cancer cells with FGFR3 activation." (PMID 34885226, 2021).